CRP (C-reactive protein)
Diseases named in the same sentence as CRP in open-access papers (continued):
Sharing a sentence is not in itself a finding about the gene and the disease.
bone metastasis (continued). "This study showed that patients without CN and with bone metastasis, liver metastasis, high CRP levels and paraneoplastic symptoms were significantly correlated with PFS." (PMID 38651176, 2024). "CRP, GPS, and bone metastasis are easily identifiable and objective clinical parameters." (PMID 22103888, 2011). "Additionally, patients without CN, bone metastasis, and high CRP levels at the initiation of ipilimumab and nivolumab treatment had shorter PFS." (PMID 38651176, 2024).
cardiac hypertrophy (19 papers, 2013 to 2025). "The independent association between CRP level and cardiac hypertrophy is consistent with previous results." (PMID 35535358, 2022). "CRP may play a pathogenic role in the development of cardiac hypertrophy and fibrosis, possibly through the activation of the nuclear factor kappa B (NF-κB) signaling pathway." (PMID 40299679, 2025). "CRP is a well-known inflammatory parameter, and the excessive or remnant inflammatory status appeared to affect liver hypertrophy." (PMID 35755162, 2022). "Multiple pathophysiologic mechanisms linking inflammation and LVH have been proposed, confirming that cardiac hypertrophy may be at least partially attributable to elevated hs-CRP levels." (PMID 39819254, 2025). "Therefore, in the present study, MMP9 and sST2, promising biomarkers for cardiac fibrosis and hypertrophy, and CRP, a conventional biomarker for inflammation, were measured in addition to echocardiography." (PMID 39264503, 2025). "Changes in inflammatory markers (such as C-reactive protein (CRP), interleukin-6 (IL-6), and tumor necrosis factor-α (TNF-α)) are associated with long sleep duration, which may contribute to ventricular hypertrophy." (PMID 38131034, 2023). "It is speculated that CRP signals cardiac hypertrophy by promoting phosphatidylinositol-3 kinase activity, inducible nitric oxide synthase, mitogen-activated protein kinase pathway, and nuclear factor κ-B." (PMID 35535358, 2022). "Cardiac hypertrophy was induced in the zebrafish following a pretreatment with erythromycin (ERY), and the onset and reconciliation of disease by YDR were determined using a treadmill electrocardiogram, heart anatomy analysis, C-reactive protein release, and platelet aggregation time-analysis." (PMID 32295034, 2020).
Cerebral ischemia (19 papers, 2013 to 2025). Restriction of arterial blood supply to the brain associated with insufficient oxygenation to support the metabolic requirements of the tissue. "In systemic parameters linked to glucose metabolism, cerebral ischemia resulted in increased circulation levels of CRP and free fatty acids in rats, and the increments were alleviated by AG490." (PMID 34943061, 2021). "Recent experimental studies revealedthat C-reactive protein itself may cause additional damage to the brain after localized cerebral ischemia, potentially via acomplement-mediated aggravation of tissue injury." (PMID 40092874, 2024). "A previous study assessed the role of CRP, leukocyte count, and d-dimer as predictors of delayed cerebral ischemia (DCI)." (PMID 39001884, 2024). "Upon cerebral ischemia, rats increased their circulating levels of corticosterone, free fatty acids, and CRP, and decreased their plasma levels of FGF-21, while maintaining a constant level of FGF-15." (PMID 34073455, 2021). "The circulating levels of CRP, free fatty acids, and corticosterone were elevated in rats with cerebral ischemia, with the increments being alleviated by propranolol." (PMID 32492962, 2020). "Patients with cerebrovascular ischemia were older (P = 0.0001) and had lower serum creatinine (sCr) (P = 0.0001) and higher serum C-reactive protein (CRP) (P = 0.002) levels than normal subjects." (PMID 31830923, 2019). "Elevated levels of interleukin-6 (IL-6) and C-reactive protein (CRP) were found in the systemic circulation of SAH patients, with even higher peaks associated with delayed brain ischemia." (PMID 25110700, 2014). "Recently, it has been shown that cerebral ischemia can stimulate microglia and leukocyte to release inflammatory cytokine such as interleukin-6 (IL-6) which in turn increase the synthesis and release of C-reactive protein into the circulation." (PMID 29457029, 2017). "After cerebral ischemia, GDLM mitigates damage brought on by inflammation and oxidative stress, lessens production of inflammatory mediators like IL-6, IL-8, and CRP, and avoids oxygen radical-induced cell membrane damage, which lowers the rate of neuronal apoptosis." (PMID 38584838, 2024). "It is notable that cerebral ischemia did not change the levels of plasma proinflammatory cytokines TNF-α and IL-1β, but significantly increased the levels of plasma IL-6 and C-reactive protein, which were attenuated by propofol treatment." (PMID 24349350, 2013).
epidural abscess (19 papers, 2015 to 2026). Circumscribed collections of suppurative material occurring in the spinal or intracranial epidural space. "Elderly patients that experienced larger infusion volume, blood loss, transfusion, epidural abscess, and higher CRP underwent extended LOS as the patient with the higher SHAP value (i.e., 0.898)." (PMID 39054495, 2024). "Based on our study, we suggest that initial presenting BT, and CRP as well as existence of epidural abscess can be a significant risk factor for predicting failure of conservative treatment and necessity of surgical treatment." (PMID 37464374, 2023). "We identified 11 key features, including CRP, transfusions, infusion volume, blood loss, X-ray bone bridge, X-ray osteophyte, CT-vertebral destruction, CT-paravertebral abscess, MRI-paravertebral abscess, MRI-epidural abscess, and postoperative drainage." (PMID 39054495, 2024). "The final training and testing dataset was composed of 11 variables, which are CRP, transfusions, infusion volume, blood loss, X-ray bone bridge, X-ray osteophyte, CT-vertebral destruction, CT-paravertebral abscess, MRI-paravertebral abscess, MRI-epidural abscess, postoperative drainage." (PMID 39054495, 2024). "The study included a cohort of 580 patients and 11 features include (CRP, transfusions, infusion volume, blood loss, X-ray bone bridge, X-ray osteophyte, CT-vertebral destruction, CT-paravertebral abscess, MRI-paravertebral abscess, MRI-epidural abscess, postoperative drainage) were selected." (PMID 39054495, 2024). "The top five risk factors contributing to prolonged LOS are infusion volume, transfusions, MRI epidural abscess, C-reactive protein (CRP), and CT vertebral destruction." (PMID 39054495, 2024). "A spinal epidural abscess, a multilevel affection of the infection, and an elevated CRP value were also found in patients with a co-existing oral cavity infection." (PMID 38398352, 2024). "When considering a spinal epidural abscess diagnosis, C-reactive protein levels will almost always be elevated; however, C-reactive protein lacks specificity." (PMID 38882974, 2024). "It is well known that the C-reactive protein (CRP) is elevated in more than 90% of cases with epidural abscess and PVO and is considered as the most specific marker for treatment response." (PMID 35536406, 2022). "Severe neurological deficits are more common in the cervical and thoracic spine, in infection with S. aureus, in the presence of epidural abscess, and when CRP is higher than 150 mg/L." (PMID 34439638, 2021). "C-reactive protein (CRP) levels higher than 50 mg/L as well as the presence of a paravertebral phlegmon, soft tissue abscess, or epidural abscess are correlated with a higher rate of positive biopsy results." (PMID 34862958, 2021). "In this study, similar results were presented with a larger extent of the affected lesion, presence of epidural abscess, worse back pain, and higher initial CRP level in the CP group." (PMID 33297994, 2020). "Cost-effective yet sensitive tests such as erythrocyte sedimentation rate (ESR) and C-reactive protein (CRP) can help guide further investigation of epidural abscesses in such patients." (PMID 32368426, 2020). "CT features (non-sclerotic endplate erosions (NSEs)), magnetic resonance criteria (paravertebral/epidural abscess (PA/EA) formation), and clinical data (C-reactive protein (CRP) > 50 mg/L) were assessed for their predictive potential." (PMID 31877797, 2019). "Factors associated with SND are involvement of upper spine (cervical or thoracic), high level of CRP at diagnosis, implication of S. aureus, and the presence of epidural abscess on MRI." (PMID 28538361, 2017). "SND is more common in cervical, thoracic, and S. aureus PVO, in the presence of epidural abscess, and when CRP >150 mg/L." (PMID 28538361, 2017).
epidural abscess (continued). "In this large, retrospective, multicenter study, our results showed that PVO complicated with SND are more common in thoracic PVO, with infection due to S. aureus, in the presence of epidural abscess, in the presence of CRP level >150 mg/L." (PMID 28538361, 2017). "In another study, patients with GNB pyogenic spondylitis had a lower prevalence of spinal epidural abscesses, paraspinal abscesses, WBC counts, and CRP values compared with methicillin-susceptible S. aureus (MSSA) pyogenic spondylitis." (PMID 25978839, 2015). "In case of lesion enhancement after injection of gadolinium or suspicion of epidural abscess dosage of infectious laboratory markers would be systematic (C- reactive protein, erythrocyte sedimentation rate)." (PMID 26491523, 2015). "Furthermore, the CRP-to-albumin ratio is a valuable metric for monitoring spinal epidural abscesses." (PMID 41031628, 2025). "In addition, surgical treatment should be considered as early when patient presents initially elevated CRP and high BT with epidural abscess for the better clinical outcome for pyogenic spondylitis." (PMID 37464374, 2023). "Risk factors for SND were epidural abscess [adjusted odds ratio, aOR 8.9 (3.8–21)], cervical [aOR 8.2 (2.8–24)], and/or thoracic involvement [aOR 14.8 (5.6–39)], S. aureus PVO [aOR 2.5 (1.1–5.3)], and CRP >150 mg/L [aOR 4.1 (1.9–9)]." (PMID 28538361, 2017). "Risk factors for SND were epidural abscess [adjusted odds ratio, aOR 8.9 (3.8–21)], cervical [aOR 8.2 (2.8–24)], and/or thoracic involvement [aOR 14.8 (5.6–39)], Staphylococcus aureus PVO [aOR 2.5 (1.1–5.3)], and C-reactive protein (CRP) >150 mg/L [aOR 4.1 (1.9–9)]." (PMID 28538361, 2017).
gangrene (19 papers, 2009 to 2026). Death of tissue, usually in considerable mass and generally associated with loss of vascular (nutritive) supply and followed by bacterial invasion and putrefaction. "This approach resulted in complete ulcer healing by October 2024, with the resolution of gangrene, an 87% reduction in CRP levels (to 12 mg/L), normalization of coagulation markers, and preservation of foot function—thus preventing amputation." (PMID 40937418, 2025). "Clinical evaluation indicated extensive gangrene affecting the first and second toes, elevated inflammatory markers (C-reactive protein at 95.57 mg/L and fibrinogen at 8.18 g/L), and cardiovascular compromise (brain natriuretic peptide at 4869 pg/mL)." (PMID 40937418, 2025). "Inflammatory markers: Blood tests, such as C-reactive protein (CRP) and erythrocyte sedimentation rate (ESR), can be elevated in the presence of infection or inflammation associated with gangrene." (PMID 38116352, 2023). "The high level of inflammatory markers (elevated CRP) could represent the systemic inflammatory response to the gangrene." (PMID 40505446, 2025). "Moreover, a significant association was observed in our cohort study between perforation/gangrene and experiencing symptoms for more than a day, raised level of CRP, and increased body temperature, and this correlation was documented by previous studies." (PMID 37817011, 2023). "The inflammatory markers (CRP, WBC, PCT, NLR, PLR, and SII) of the gangrene group were higher than those of the non-gangrene group." (PMID 41163918, 2025).
Hyperkalemia (19 papers, 2014 to 2025). An abnormally increased potassium concentration in the blood. "In patients with hyperkalemia, a severe inflammatory syndrome was noted, with C-reactive protein reaching a maximum value of 38.97 mg/dL and a median of 22.09 mg/dL (IQR: 4.36–26.71 mg/dL), much higher than the average of the entire group." (PMID 39451561, 2024). "The blood test found leukocytes at 156 × 109/L consisting of 12.8 × 109/L neutrophils and 140 × 109/L lymphocytes, serum biochemical analysis with creatinine level at 160 μmol/L, hyperkalemia at 5.3 mmol/L, and elevated C-reactive protein (CRP) at 271 mg/L." (PMID 34253232, 2021). "The most common (≥1%) events were palmar-plantar erythrodysaesthesia syndrome (16 [1.6%] patients), hyperkalaemia (13 [1.3%] patients) and dyspnoea, constipation and C-reactive protein increased (11 [1.1%] patients each)." (PMID 32458996, 2020). "Laboratory evaluation showed elevated creatinine of 1.88 mg/dL (baseline creatinine level of 1.1 mg/dL), mild hyperkalemia of 5.3 mEq/L, elevated erythrocyte sedimentation rate (ESR) of 75 mm/hr, elevated C-reactive protein (CRP) of 2.5 mg/dL, normal complete blood count and coagulation panel." (PMID 37485225, 2023).
hyperphosphatemia (19 papers, 2015 to 2026). Abnormally high level of phosphate in the blood. "Conversely, in targeted models of increasing complexity, inflammatory indexes (hs-CRP and ferritin) and hyperphosphatemia remained significantly associated with cIMT severity only if Omentin-1 was not introduced in the model." (PMID 35888609, 2022). "In the multivariate analysis focusing on biochemical parameters (“Biochemical” model), a high eGFR at DI, hyperphosphatemia (> 2.0 mmol/L), low serum albumin (< 33 g/L), and elevated CRP (> 10 mg/L) associated independently with mortality." (PMID 35761193, 2022). "Independent factors predicting death were high age, comorbidity, clinical contraindications to PD or HD, suboptimal DI, high eGFR, low serum albumin, hyperphosphatemia, high C-reactive protein, signs of overhydration and cerebral symptoms at DI." (PMID 35761193, 2022). "As a comparison, our patients with severe SHPT (iPTH>1,000pg/mL) presented more hyperphosphatemia and hypovitaminosis D. High levels of CRP and ferritin found in our population strongly suggest chronic inflammation." (PMID 33979425, 2021). "The prevalence and severity of albuminuria (p<0.0003), hyperphosphatemia (p<.0001), hyperparathyroidism (p<0.0001), and metabolic acidosis (p<0.0009) increased with decreasing eGFR, whereas serum albumin, 25OHD, and CRP were not statistically significantly associated with renal function." (PMID 25659076, 2015).
Jaundice (19 papers, 2018 to 2025). Yellow pigmentation of the skin due to bilirubin, which in turn is the result of increased bilirubin concentration in the bloodstream. "The risk of jaundice decreased when the CRP level was ≥5 mg/dL compared to that when the CRP level was < 5 mg/dL [OR = 0.34; 95% CI, 0.20–0.61; p = 0.001]." (PMID 30501619, 2018). "Female, BMI ≥ 25, preoperative jaundice state, pancreatic texture, diameter of pancreatic duct, the techniques of pancreatic anastomosis, and CRP ≥ 180 mg/L were enrolled into the multivariate analysis model." (PMID 35860201, 2022). "Out of 29 candidate variables, 17 were retained in the final STm, of which a raised C-reactive protein (4.09 (3.24 to 5.16) and concurrent jaundice (2.33 (1.27 to 4.28)) were most predictive." (PMID 34464384, 2021). "Moreover, as CRP is derived from the liver, it is substantially influenced by the presence of jaundice making it unreliable in patients with this comorbidity." (PMID 36969742, 2022). "Forty-three percent of patients had an elevated C-reactive protein (CRP), 34 percent had an elevated white cell count (WCC), 27 percent had deranged liver function tests, and 11 percent had clinical jaundice." (PMID 37046466, 2023). "Additionally, the AKI group presented more jaundice cases, higher sting numbers/BSA, higher levels of CRP, ALT, AST, TBIL, LDH, cTnI, and CK." (PMID 38196017, 2024). "Considering that infection is one of the main causes of neonatal jaundice, we further analyzed the relationship between neonatal laboratory results and jaundice, and found that CRP level was positively correlated with the disease (data not shown)." (PMID 34368025, 2021). "CRP level was significantly different in the jaundice group at 2.1 ± 0.4 mg/L and non-jaundice group at 7.2 ± 0.9 mg/L (p = 0.001)." (PMID 30501619, 2018). "CRP exhibited a significant nonlinear relationship with infection risk (P < 0.001) and was included as a spline term, while an interaction term between ALB and jaundice was incorporated." (PMID 41167422, 2025).
Osteopenia (19 papers, 2015 to 2026). Osteopenia is a term to define bone density that is not normal but also not as low as osteoporosis. "Similarly, SBP (>120 mmHg), TG (>150 mg/dl), poor sleep (>5 scores), higher CRP (>3 mg/L) and lower femoral neck BMD (<0.7 g/cm2) and BMD at lumbar spine (<0.8 g/cm2) were independent risk factors for the risk of osteopenia." (PMID 35270692, 2022). "However, in contrast to the literature, CRP was lower in the osteoporotic women than those with osteopenia or healthy bone." (PMID 31333751, 2019). "Our study examined the relationship between C-reactive protein-triglyceride-glucose index (CTI) levels and osteopenia/OP in middle-aged and elderly individuals with T2DM." (PMID 41179881, 2025).